RNU4-73P (RNA, U4 small nuclear 73, pseudogene)
Gene: Small nuclear RNA gene on chromosome 2 (9,740,643 to 9,740,783, reverse strand). Ensembl gene ENSG00000200034.
Homologues: Orthologues: macaque U4 (96% identical), rat LOC120098738 (80% identical). Paralogues in human: RNU4-67P (79% identical), RNU4-13P (77% identical), RNU4-44P (77% identical), RNU4-58P (77% identical), RNU4-68P (76% identical), RNU4-42P (75% identical), RNU4-7P (75% identical), RNU4-84P (75% identical), RNU4-80P (74% identical), RNU4-8P (74% identical), RNU4-56P (73% identical), RNU4-76P (73% identical), and 81 more.